AGTR1 (angiotensin II receptor type 1)
Diseases named in the same sentence as AGTR1 in open-access papers (continued):
Sharing a sentence is not in itself a finding about the gene and the disease.
cancer (continued). "Since AGTR1 plays an important role in cancer progression, the knockdown of AT1R could potentially be an advantageous complementary treatment strategy." (PMID 37291545, 2023). "As an important gene in the RAS system, AGTR1 also plays an important role in various cancers." (PMID 36983741, 2023). "Previous evidence demonstrates that AGTR1 exerts a crucial role in facilitating cancer progression." (PMID 35910032, 2022). "On the contrary, AGTR1 was correlated with the fewest types of cancer." (PMID 35513851, 2022). "AGTR1 is expressed in several cancers, such as ovarian carcinoma." (PMID 34095461, 2021). "ACEIs/ARBs (ACE/ANG II/AGTR1 axis inhibitors) might benefit cancer patients with SARS-CoV-2 infection." (PMID 34671200, 2021). "Alterations in the Ca2+ signaling pathway were observed in nine cancer types and AGTR1 GRIN2A (Glutamate Ionotropic Receptor NMDA Type Subunit 2A), ITPKB (Inositol-Trisphosphate 3-Kinase B), and SLC8A3 (Solute Carrier Family 8 Member A3) were repressed by hypermethylation in six of them." (PMID 32629766, 2020). "Yet, we also recognized that there was a growing body of literature implicating both angiotensin II and its receptor AGTR1 as key players in the pathogenesis of a variety of cancers, including squamous cell carcinoma of the skin, glioblastoma, gastric cancer, ovarian cancer, and others." (PMID 30158935, 2018). "Similarly, angiotensin II receptor 1 (AGTR1) was identified by our method as being shared by 5 different cancer types." (PMID 28178311, 2017). "One possible explanation of the predicted ARB effects on CRCs is that ARB drugs may have other targets in addition to AGTR1, and exert their anti-cancer effects via those unknown targets independently of AGTR1." (PMID 27965461, 2017). "Specifically, five cancer types shared a change in AGTR1 and IGF1 genes, which implies that there may be similar underlying disease mechanisms among these cancers." (PMID 28178311, 2017). "Survival analysis (from The Cancer Genome Atlas database) found that the expression level of AGTR1 is directly related to the overall survival and disease-free survival rate and that high AGTR1 expression indicates an unfavorable prognosis." (PMID 28439256, 2017). "Specifically, AngII–AGTR1 axis could be further explored as a potential therapeutic target for treating AGTR1 positive cancers including AGTR1 and ER-positive BCa." (PMID 25981295, 2015). "RAS encompasses multiple axes, among which the AngII signaling through its receptors AGTR1 and AGTR2 has been the subject of extensive research, where this axis is known to intersect with a variety of pathways implicated in tumorigenesis, highlighting its potential role in cancer biology." (PMID 40099255, 2025). "Additionally, A-II induces cancer cell growth and invasion via AGTR1." (PMID 30564297, 2018). "Taken together, ACE and AGTR1 blockers could be used as an adjuvant therapy along with established chemotherapeutic drugs to further potentiate the anti-cancer effects of the conventional cancer therapies." (PMID 25981295, 2015). "Taken together, our data offer molecular evidence that the increase in MAS1 expression is able to suppress the AGTR1‐mediated SRE activity and the calcium response via formation of receptor heterocomplexes in cancer cells." (PMID 35712764, 2022). "Among four novel methylation markers in OPSCC (AGTR1, CSGALNACT2, GULP1 and VGF), AGTR1 showed a significant correlation with cancer specificity, HPV infection specificity and p16 + /RB- phenotype." (PMID 36344942, 2022). "Angiotensin II receptor type 1 (AGTR1), a receptor for angiotensin II, is capable of prompting EMT, anchorage-independent growth, and metastasis in cancer." (PMID 33435156, 2021). "The oncoprint displayed an overall alteration frequency of RAS family of 15.2% in TCGA pan-cancer across TCGA cancers, with the highest frequency existing for ACE (4%), followed by AGT (3%), AGTR1 (3%), ACE2 (2.3%), AGTR2 (1.5%) and MAS1 (1.4%)." (PMID 34671200, 2021).
cancer (continued). "In this study, we comprehensively integrated and analyzed the molecular characteristics of 6 significant members of the RAS family across pan-cancer: AGT, ACE, ACE2, AGTR1, AGTR2, and MAS1." (PMID 34671200, 2021). "AGTR1 can also promote lymph node metastasis by chemokine CXCR4/SDF-1α increases, presenting a cancer-promoting effect." (PMID 34568039, 2021). "AGTR1 was expressed in ACC, LIHC, and corresponding cancer cell lines." (PMID 34671200, 2021). "Finally, we discovered eight genes (MME, SOX17, AGTR1, PGR, ESR1, PAX8, C3 and IRF6) with high amplification frequency compared to other genes across the cancer types." (PMID 31879572, 2019). "Thus, we observed that the AGTR1 (GPCR protein) and IGF1 genes were shared by 5 different cancer types, which are shown in red." (PMID 28178311, 2017). "For example, AGTR1, GRIN2A, ITPKB, and SLC8A3 were repressed by hypermethylation in six cancer types, and ADCY4, ADCY8, BST1, and PRKCB were inhibited by hypermethylation in five cancer types." (PMID 28060724, 2017). "Nevertheless, a deeper and comprehensive understanding of AngII–AGTR1 axis and AGTR1–EGFR crosstalk in the context of AGTR1 positive cancers may direct future studies, which may lead to the development of novel drug targets against these pathways as an alternative to existing cancer therapies." (PMID 25981295, 2015). "AGTR1 and ACE2 showed a negative correlation in most cancers." (PMID 34671200, 2021).
cardiovascular diseases (114 papers, 2007 to 2026). "The previous findings correlating the A1166C AGTR1 gene polymorphism with cardiovascular diseases are contradicting." (PMID 35886041, 2022). "Angiotensin II receptor type 1 (AGTR1) is a significant effector of the renin-angiotensin-aldosterone system, which is associated with cardiovascular diseases, especially cardiac remodeling." (PMID 34765659, 2021). "The AGTR1 gene encodes angiotensin II receptor type 1, which is involved in cardiovascular diseases." (PMID 34781995, 2021). "This polymorphism can disrupt miR-155 regulation of AGTR1, leading to increased expression which contributes to vasoconstriction and increases the risk for cardiovascular disease." (PMID 29762500, 2018). "Genetic polymorphisms of AGTR1 have been found to be closely related to cardiovascular diseases, metabolic disorders and even longevity in previous studies." (PMID 27240348, 2016). "The interaction between AGTR1(1166 A > C) genotype and drug use underscores the potential of personalized medicine in optimizing cardiovascular disease prevention strategies in primary care." (PMID 41968188, 2026). "The AGTR1 gene mediated by the renin–angiotensin system is crucial to the pathophysiology of cardiovascular diseases." (PMID 36831718, 2023). "Systemic manipulation of the RAS, especially by interfering with the signaling of angiotensin II (AngII) at the angiotensin II receptor type 1 (AT1R), is now a mainstay of treatment in cardiovascular disease." (PMID 32324784, 2020). "There is evidence of association of AGTR1 1166 A>C and ACE I/D polymorphisms with CKD and cardiovascular diseases, their roles in non-BP dipping at night, and nocturnal hypertension, but this remain unclear among African blacks." (PMID 31951214, 2020).
renal disease (55 papers, 2009 to 2025). "The A allele in AGTR1 rs5186 acted as a protection factor for renal disease development in South Asian population." (PMID 31048445, 2019). "This meta-analysis of AGTR1 variants included 3197 individuals with renal disease and 3720 controls investigating rs5186." (PMID 31048445, 2019). "AGTR1 (angiotensin II receptor, type 1) is associated with renal tubular dysgenesis, an autosomal recessive severe kidney disorder characterized by abnormal development of the kidneys before birth." (PMID 26179878, 2015). "The three remaining RAAS genes included in this meta-analysis, ACE2, AGTR2 and REN, have not been researched as extensively as ACE, AGT and AGTR1 for associations with renal disease." (PMID 31048445, 2019). "Network pharmacology analysis showed significant biological interaction of NEERI KFT metabolites, especially polyphenols, which regulate the expression of several genomes (CASPs, ILs, AGTR1, AKT, ACE2, SOD1, etc.)that are involved in the pathophysiology of kidney disease." (PMID 36672676, 2023). "The results showed that gallic acid exhibits a significantly strong interaction with genes such as CASPs, ILs, AGTR1, ACE2, SOD1, etc., while caffeic acid and ferulic acid showed comparatively low interaction with the genes involved in the pathophysiology of the kidney disease." (PMID 36672676, 2023). "Rizzo's research has also revealed the close relationship between Ang II/AGTR1 and SDF-1α/CXCR4 in kidney diseases, indicating that increased Ang II could activate podocytes to release SDF-1α, which binds to its receptor CXCR4 located on parietal epithelial cells (PECs)." (PMID 31219799, 2019).
infection (30 papers, 2010 to 2024). The state of being infected such as from the introduction of a foreign agent such as serum, vaccine, antigenic substance or organism. "Before infection, AGTR1 levels ranged from 232.1 to 336.2 ng/mL of plasma (mean ± SE: 298.6 ± 11.5 ng/mL)." (PMID 35281029, 2022). "We also observed a significantly reduced AGTR1 plasma level compared with pre infection at 21 dpi (p = 0.0006), 40 dpi (p = 0.0086), 90 dpi (p = 0.0220), 112 dpi (p = 0.0021), and 180 dpi (p < 0.0001)." (PMID 35281029, 2022). "AGTR1 level reduced during infection with the lowest at 180 dpi (mean ± SE: 227.3 ± 8.8 ng/mL)." (PMID 35281029, 2022). "Plasma AGTR1 concentrations were measured in 10 subjects at pre and post infection time points." (PMID 35281029, 2022). "Infection with SARS-CoV-2 stimulates the RA system module, which potentiates inflammation through specific mediators and effectors, like AGTR1/2." (PMID 38414974, 2023).
heart disease (11 papers, 2011 to 2025). "Together, these data allowed testing of the ACE I/D and AGTR1 polymorphisms as risk factors for susceptibility to Chagas’ heart disease and progression to severe CARD with HFrEF in this population." (PMID 39591456, 2024).
neurodegenerative disease (10 papers, 2014 to 2026). A disorder of the central nervous system characterized by gradual and progressive loss of neural tissue and neurologic function. "AGTR1, also known as angiotensin II receptor type 1, has been extensively studied in tumors and neurodegenerative diseases." (PMID 37508947, 2023).
inflammation (8 papers, 2012 to 2025). Aberrant reaction of the microcirculation characterized by movement of fluid and leukocytes from the blood into extravascular tissues. "SNPs in PNPLA3, TNF-α, AGTR1, IL-17A, IL-1B, PTPRD, and GATAD2A cause liver inflammation." (PMID 36000237, 2022).
brain disorder (6 papers, 2020 to 2024). A disease affecting the brain or part of the brain. "Others include NOS2, an important signaling molecule of the central nervous system associated with neurotransmission and diverse brain disorders, and AGTR1, which is associated with susceptibility to brain neurodegeneration." (PMID 38532526, 2024).
retinopathy (4 papers, 2015 to 2025). "Specific blockade of the RAS with the Angiotensin II receptor type 1 (AT1R) blocker (Losartan, Candesartan) and angiotensin-converting enzyme inhibitor (Enalapril) has been shown to reduce the risk of onset and the progression of retinopathy in patients with type 1 and 2 diabetes." (PMID 29565290, 2018).
AGTR1 also shares sentences with these, for which no sentence is quoted: kidney damage (31 papers); chronic kidney disease (28); Cognitive impairment (24); metabolic syndrome (23); metabolic disorders (21); ischemia (20); type 2 diabetes (15); kidney (11); Anxiety (10); diabetic cardiomyopathy (10); malignant hypertension (10); renovascular hypertension (10); acute myocardial infarction (9); glomerular disease (9); injury (9); myocardial ischemia (9); abdominal aortic aneurysm (8); Cerebral ischemia (8); colitis (8); depression (8); dilated cardiomyopathy (8); vasculopathy (8); autoimmune disease (7); focal segmental glomerulosclerosis (7); hypertrophy (7); non-small cell lung carcinoma (7); osteoporosis (7); portal hypertension (7); renal failure (7); vascular hypertrophy (7).
A further 282 diseases each share a sentence with AGTR1 in 6 papers or fewer.